FRS2 (fibroblast growth factor receptor substrate 2)
Description:
Adapter protein that links activated FGR and NGF receptors to downstream signaling pathways. Plays an important role in the activation of MAP kinases and in the phosphorylation of PIK3R1, the regulatory subunit of phosphatidylinositol 3-kinase, in response to ligand-mediated activation of FGFR1. Modulates signaling via SHC1 by competing for a common binding site on NTRK1.
Synonyms: SNT-1; FRS2alpha; SNT1; FRS2A; FRS1A; SNT
Tractability: Antibody: its Gene Ontology location is reachable by antibodies, with high confidence. PROTAC: UniProt records ubiquitination sites on it; ubiquitination databases record sites on it; its protein half-life has been measured; a small molecule that binds it is known.
Gene: Protein-coding gene on chromosome 12 (69,470,349 to 69,579,793, forward strand). Ensembl gene ENSG00000166225.
Subcellular location: Endomembrane system
Subcellular location (Human Protein Atlas): Cell Junctions; Plasma membrane
Pathways (Reactome):
Signal Transduction: Activated NTRK2 signals through FRS2 and FRS3; FRS-mediated FGFR1 signaling; FRS-mediated FGFR2 signaling; FRS-mediated FGFR3 signaling; FRS-mediated FGFR4 signaling; Frs2-mediated activation; Negative regulation of FGFR1 signaling; Negative regulation of FGFR2 signaling; Negative regulation of FGFR3 signaling; Negative regulation of FGFR4 signaling; PI-3K cascade:FGFR1; PI-3K cascade:FGFR2; PI-3K cascade:FGFR3; PI-3K cascade:FGFR4; PI3K Cascade; PI5P, PP2A and IER3 Regulate PI3K/AKT Signaling; PIP3 activates AKT signaling; RAF/MAP kinase cascade; RND1 GTPase cycle; RND2 GTPase cycle; Signaling by ALK
Disease: Constitutive Signaling by Aberrant PI3K in Cancer; Signaling by ALK fusions and activated point mutants; Signaling by FGFR1 in disease; Signaling by FGFR2 in disease; Signaling by FGFR3 in disease; Signaling by FGFR4 in disease
Developmental Biology: RET signaling
Gene Ontology:
Molecular function: fibroblast growth factor receptor binding; neurotrophin TRKA receptor binding; protein binding; phosphatase activator activity; transmembrane receptor protein tyrosine kinase adaptor activity
Biological process: fibroblast growth factor receptor signaling pathway; negative regulation of cardiac muscle cell differentiation; cell surface receptor protein tyrosine phosphatase signaling pathway; G protein-coupled receptor signaling pathway
Cellular component: adherens junction; cell-cell junction; cytosol; membrane; plasma membrane; cytoplasm; endomembrane system
Genetic constraint (gnomAD): Loss-of-function variants: 6 observed, 30.23 expected, observed/expected ratio (o/e) 0.2, 90% interval 0.11 to 0.39. The upper end of that interval is the gene's LOEUF score, 0.39, which puts it in group 1 of 6, group 1 being the genes least tolerant of losing a copy. Missense variants: 420 observed, 515.41 expected, observed/expected ratio (o/e) 0.81, 90% interval 0.75 to 0.88. Synonymous variants: 171 observed, 186.92 expected, observed/expected ratio (o/e) 0.91, 90% interval 0.81 to 1.04.
Homologues: Orthologues: macaque FRS2 (99% identical), chimpanzee FRS2 (99% identical), dog FRS2 (99% identical), guinea pig FRS2 (98% identical), pig FRS2 (98% identical), mouse Frs2 (96% identical), rat Frs2 (95% identical), rabbit FRS2 (90% identical), tropical clawed frog frs2 (82% identical), zebrafish frs2a (66% identical), zebrafish frs2b (60% identical), Caenorhabditis elegans rog-1 (18% identical), and 2 more. Paralogues in human: FRS3 (47% identical), DOK1 (14% identical), DOK3 (12% identical), DOK2 (11% identical), DOK4 (9% identical), DOK6 (9% identical), DOK5 (8% identical).
Diseases named in the same sentence as FRS2 in open-access papers:
FRS2 is named in the same sentence as 57 diseases in open-access papers, as found by Europe PMC text mining. Sharing a sentence is not in itself a finding about the gene and the disease. The quoted sentences say what the papers report.
liposarcoma (14 papers, 2015 to 2025). A usually painless malignant tumor that arises from adipose tissue. "Amplification of FRS2 in liposarcoma has been documented 25, and we aim to evaluate its prognostic value and potential as a novel therapeutic target for TKI-based treatments." (PMID 40225873, 2025). "Many genetic mutations have been reported in dedifferentiated liposarcomas, including mutations in MDM2, CDK4, high mobility group AT-hook 2 (HMGA2), fibroblast growth factor receptor substrate 2 (FRS2), and neuron navigator 3 (NAV3), all located in 12q13-15." (PMID 35008848, 2021). "Meanwhile FGFR-specific downstream signaling adaptor, FGFR substrate 2 (FRS2), is overexpressed in liposarcoma and renders these cells sensitive to FGFR inhibitors." (PMID 35071225, 2021). "In summary, our results support LY2874455 as a better drug candidate than NVP-BGJ398 for treatment of FRS2-amplified liposarcoma." (PMID 30795553, 2019). "Other notable mutations include three FRS2 and FGF co-amplifications seen in a rhabdomyosarcoma, osteosarcoma, and dedifferentiated liposarcoma." (PMID 28424409, 2017). "As another member of adaptor proteins, FRS2 was amplified in various human cancers, including ovarian cancer, liposarcoma and glioma." (PMID 28558797, 2017). "Additionally, FRS2-mediated signals were validated to promote tumour angiogenesis and predict poor prognosis in prostate carcinoma, high-grade serous ovarian cancer and liposarcoma." (PMID 35440045, 2022). "Fibroblast growth factor receptor substrate 2 (FRS2), located near MDM2 on chromosome 12q13-15, has a biological role and prognostic value in liposarcoma, which remain to be fully explored." (PMID 40225873, 2025). "FGF receptor (FGFR) substrate 2 (FRS2) is located on chromosome 12q13-15, which is frequently amplified in liposarcomas as previously outlined." (PMID 34068344, 2021). "Previous studies have shown that FRS2 and FGFR are highly expressed and active in several high-grade liposarcomas, and targetable by the FGFR inhibitor NVP-BGJ398 in DDLPS cell lines in vitro." (PMID 27409346, 2016). "Fibroblast growth factor receptor substrate 2 (FRS2), an adaptor protein that plays a critical role in FGFR signaling is also located on chromosome 12q13-15 and reported to be frequently amplified in high-grade liposarcomas." (PMID 29731991, 2018). "FRS2 gene was recently found to be consistently amplified in atypical lipomatous tumor (ALT)/well-differentiated liposarcoma (WDL) and dedifferentiated liposarcoma (DDL), suggesting the detection of FRS2 amplification could be a diagnostic tool for ALT/WDL/DDLs." (PMID 34696768, 2021).
breast cancer (13 papers, 2013 to 2025). A primary or metastatic malignant neoplasm involving the breast. "Furthermore, both breast cancer mutations implicated an increased tyrosine phosphorylation of the critical FGFR2 substrate FRS2 and an increased MEK1/2 and STAT3 activation in response to FGF1 stimulation leading to an accelerated cell signaling." (PMID 23527311, 2013). "Other altered genes in these patients are FRS2, LYZ, and CPSF6, all associated to breast cancer pathogenesis." (PMID 36860495, 2022). "The Giα proteins associated with RTKs, Gab1, FRS2 and Shp2 in breast cancer cells and their ablation impaired Gab1’s interactions with Shp2 in response to EGF and IGF-1, or with FRS2 and Grb2 in response to bFGF." (PMID 24521094, 2014). "However, the roles of FRS2 in endocrine resistance in breast cancer are unclear." (PMID 27533459, 2016). "Via activation of the FRS2‐ERK signaling, FGFR4 induced breast cancer doxorubicin (ADR) resistance and promoted glucose metabolism." (PMID 39658878, 2024). "The MAP kinase adaptor proteins FRS2 and GRB7 were also highly amplified (10–20 copies in lung adenocarcinoma and breast cancer, respectively)." (PMID 24874471, 2014). "Both breast cancer mutants led to an increased tyrosine phosphorylation of FRS2, a well-characterized FGFR2 substrate, as revealed by immunoblotting with anti-p-FRS2 antibody after SDS-PAGE." (PMID 23527311, 2013). "The transcriptome biomarker profile, which includes the leucine zipper putative tumor suppressor 1, fibroblast growth factor receptor substrate 2, cyclin I, the EGF receptor, FGF-19, B-Raf gene, and growth regulation by estrogen in breast cancer 1, has been identified." (PMID 41245374, 2025). "Fibroblast growth factor receptor substrate 2 (FRS2) acts upstream of the FGF signaling pathway, is an adaptor protein expressed in a small subset of epithelial cells and triggers a cytokine-rich inflammatory microenvironment that promotes breast cancer carcinogenesis." (PMID 35804935, 2022).
osteosarcoma (9 papers, 2017 to 2025). A usually aggressive malignant bone-forming mesenchymal neoplasm, predominantly affecting adolescents and young adults. "All FRS2 promoter partner genes, with one exception, demonstrated the highest expression levels in the affected cases compared with other osteosarcomas." (PMID 39322633, 2024). "In particular, CNV was more frequent in CCND3, AURKB, CCNE1, GID4, and MYC in P-AYA, while MDM2, CDKN2A/B, and FRS2 were more frequently altered in adult osteosarcoma (p < 0.001)." (PMID 35705558, 2022). "The remaining five FRS2-rearranged cases were low-grade osteosarcomas or of low-grade origin." (PMID 39322633, 2024). "Activated FGFR4 interacts with fibroblast growth factor receptor substrate 2 (FRS2), recruits growth factor receptor binding protein (GRB2) and affects downstream proteins mediating osteosarcoma cell proliferation." (PMID 36895941, 2023). "Some scholars have found that through the FRS2/TGF−/−catenin pathway, FGF-induced LHX9 controls osteosarcoma development and migration." (PMID 36303551, 2022). "Here, we demonstrate that in NIH3T3 mouse fibroblasts and human osteosarcoma U2OS cells stably expressing FGFR1, in addition to Erk1 and Erk2, p38 kinase is able to phosphorylate FRS2." (PMID 31013829, 2019). "Among the FRS2-rearranged cases classified as conventional osteosarcoma, the consequences of a dislocated FRS2 promoter could not be determined." (PMID 39322633, 2024).
prostate carcinoma (9 papers, 2011 to 2025). A carcinoma that arises from epithelial cells of the prostate gland. "In human prostate cancer samples, high FGF9 and CX3CR1 expression was jointly associated with the FGFR1 activation marker p-FRS2." (PMID 41514658, 2025). "The positive correlation between FGF9 and p-FRS2 reached significance in CX3CR1hi prostate cancer samples and disappeared in CX3CR1lo samples." (PMID 38781024, 2024). "In prostate cancer, FRS2 signaling promotes tumor angiogenesis, and FRS2 overexpression by gene duplication in bladder cancer is associated with tumor vascularization and poor prognosis." (PMID 36495366, 2023). "In summary, our data implied that androgen suppressed PKD1 expression through an indirect FGFR/FRS2/MEK/ERK pathway in prostate cancer cells." (PMID 28077787, 2017). "This evidence supports the notion that PKD1 is repressed by an AR-induced FGFR/FRS2/MEK/ERK pathway in androgen-sensitive prostate cancer cells." (PMID 28077787, 2017). "Regardless of these discrepancies, in all cases, AR promotes the activation of FGFR in prostate cancer cells, which results in phosphorylation of FRS2 and activation of the downstream Ras/Raf/MEK/ERK signaling pathway." (PMID 28077787, 2017). "In androgen-sensitive prostate cancer cells, depletion of FRS2 blocked R1881-induced PKD1 suppression at both the transcriptional and protein levels." (PMID 28077787, 2017). "Furthermore, pharmacologically targeting the myristoylation of the FRS2 scaffold protein whose role in prostate cancer has been elaborated in Chapter 3.1, inhibits FGF/FGFR-mediated oncogenic signaling and consequently the prostate cancer progression." (PMID 33572160, 2021). "In addition, hyperactivation of the FRS2-mediated signals promoted tumor angiogenesis and predicted poor outcomes in prostate carcinoma patients." (PMID 30755618, 2019). "Thus, androgen may repress PKD1 through an AR-induced FGFR/FRS2/MEK/ERK pathway to inhibit PKD1 expression in prostate cancer cells." (PMID 28077787, 2017). "Although FIIN1/FIIN2 inhibited downstream FGFR signaling (p-FRS2α and p-ERK1/2) across the cell lines, 10 μM treatment was cytotoxic to both prostate cancer cells and CAFs." (PMID 41514658, 2025). "We found that these CM were capable of inducing FGFR1 activation in prostate cancer cells, as indicated by the phosphorylation of ERK and FGF receptor substrate 2 (FRS2)." (PMID 38781024, 2024). "FGF9 activated FGFR1 signaling in a dose-dependent manner within 15 minutes in DU 145 prostate cancer cells, as indicated by the phosphorylation of ERK and FRS2." (PMID 38781024, 2024). "Here we investigated FRS2 and FRS3 as a means of disrupting global FGF signalling in prostate cancer." (PMID 22078327, 2011). "Given evidence of expression overlap in our cell lines, we tested functional overlap between FRS2 and FRS3 in prostate cancer." (PMID 22078327, 2011). "Our results suggest that both FRS2 and FRS3 are important in FGF mediated signalling in prostate cancer." (PMID 22078327, 2011). "FRS2 and FRS3 mRNA were ubiquitously expressed in normal epithelial prostate cell lines (PNT1A/PNT2) and prostate cancer cell lines (LNCaP, DU145 and PC3)." (PMID 22078327, 2011). "We therefore tested expression of FRS2 and FRS3 transcript by quantitative real time PCR in a panel of archival clinical prostate cancers using methods previously developed in our group." (PMID 22078327, 2011). "FRS2 and FRS3 exhibit functional redundancy in prostate cancer cells and dual inhibition effectively blocks intracellular signalling and the mitogenic effects of multiple FGFs." (PMID 22078327, 2011). "Given this functional redundancy, we tested the therapeutic principle of dual targeting of FRS2 and FRS3 in prostate cancer." (PMID 22078327, 2011). "Synchronous knockdown of FRS2 and FRS3 with exposure to cytotoxic irradiation resulted in a significant reduction in prostate cancer cell survival compared to irradiation alone (p < 0.05)." (PMID 22078327, 2011).
prostate carcinoma (continued). "We have observed that combined silencing of FRS2 and FRS3 resulted in a significant inhibition in FGF induced ERK activation in prostate cancer cell lines." (PMID 22078327, 2011). "In this study we investigated the relative expression and functional role of FRS2 and FRS3 in prostate cancer." (PMID 22078327, 2011). "Furthermore, in human prostate cancer tissue assays, we detected p-AKT, FGF9, CX3CR1, and p-FRS2 with IHC staining." (PMID 38781024, 2024). "In addition, recent studies showed that pharmacologically targeting FRS2 inhibited FGF/FGFR-mediated oncogenic signaling and tumor progression in prostate cancer and gastric cancer cell lines." (PMID 34696768, 2021). "Although FRS2 expression is not regulated by androgen, androgen-sensitive prostate cancer cells express FGF2, and its expression is upregulated in response to androgen stimulation." (PMID 28077787, 2017). "In conclusion this is the first study to investigate FRS2 and FRS3 in prostate cancer." (PMID 22078327, 2011). "We next tested functional redundancy of FRS2 and FRS3 in prostate cancer cells." (PMID 22078327, 2011). "There have been very few studies of FRS2 and FRS3 in clinical cancers and no reports in prostate cancer." (PMID 22078327, 2011). "FRS2 and FRS3 suppression in contrast, did not have any appreciable effect on EGF stimulation in either of our prostate cancer cell models." (PMID 22078327, 2011). "FRS2 and FRS3 therefore do not appear to be altered in prostate cancer." (PMID 22078327, 2011).
bladder cancer (6 papers, 2019 to 2025). "Amplification of the FRS2 gene has been reported in multiple malignancies, including bladder cancer and sarcomas, and is associated with poor clinical outcomes." (PMID 40707918, 2025). "Of interest, whole-genome sequencing has identified ADGRG6 enhancer mutations and FRS2 duplications as angiogenesis-related drivers in bladder cancer." (PMID 35213989, 2022). "Our previous whole-genome sequencing study further demonstrated that FRS2 copy number can increase by 3- to 25-fold in bladder cancer tissues, and this amplification correlates with elevated microvessel density and adverse prognosis." (PMID 40707918, 2025). "In this study, we established a ddPCR-based assay to quantify FRS2 copy number in bladder cancer specimens." (PMID 40707918, 2025). "This platform offers a sensitive and reliable approach for detecting FRS2 amplification in bladder cancer." (PMID 40707918, 2025). "Functional assays have demonstrated that depletion of ADGRG6 or FRS2 expression in bladder cancer cells compromises their abilities to recruit endothelial cells and induce tube formation." (PMID 35213989, 2022). "This is consistent with a study in human bladder cancer, which showed dephosphorylation of FRS2 and ERK by NVP-BGJ398." (PMID 30795553, 2019). "The developed ddPCR assay enables accurate and reliable quantification of FRS2 copy number in FFPE samples, offering a promising tool for auxiliary diagnosis and prognostic assessment in bladder cancer." (PMID 40707918, 2025). "In addition, based on the FGFR3 fusions and overexpression of FRS2, we also included SW780 (urinary bladder carcinoma), RT-112 (urinary bladder carcinoma), M059K (glioblastoma) and SKOV3 (ovarian adenocarcinoma) cell lines." (PMID 36495366, 2023).
atherosclerosis (5 papers, 2016 to 2024). A disease characterized by the build-up of fatty material and calcium deposition in the arterial wall resulting in partial or complete occlusion of the arterial lumen. "Circ_0002984 promotes PDGF-BB-induced VSMC proliferation, migration, and invasion through the regulation of the miR379-5p/fibroblast growth factor receptor substrate 2 (FRS2) axis, suggesting a novel pathogenesis of atherosclerosis." (PMID 39595622, 2024). "In addition, it has been demonstrated that lncRNA ANRIL promoted cell proliferation and migration via sponging miR‐339‐5p and regulating FRS2 expression in atherosclerosis." (PMID 32515146, 2020). "In vivo, SMC FRS2α deletion decreased the extent of atherosclerosis in Apoe−/− mice." (PMID 27189169, 2016). "Moreover, several target genes of miR-92a have been determined to be involved in the regulation of atherosclerosis and CAS, such as phosphatase and tensin homolog (PTEN), SMAD family member 7 (SMAD7) and fibroblast growth factor receptor substrate 2 (FRS2)." (PMID 32522208, 2020).
gastric cancer (4 papers, 2014 to 2021). A primary or metastatic malignant neoplasm involving the stomach. "Similar to our results, high expression and carcinogenesis of FRS2 was found in Wilms' tumor and gastric cancer." (PMID 32515146, 2020).
lung carcinoma (4 papers, 2022 to 2025). "The non-invasive and affordable diagnosis of lung cancer can beaided by salivary mRNA biomarkers (CCNI, EGFR, FGF19, FRS2, and GREB1)." (PMID 37693919, 2022). "The logistic regression model combining the five mRNA biomarkers (CCNI, EGFR, FGF19, FRS2, and GREB1) can distinguish patients with lung cancer from normal controls (area under the receiver operating characteristic curve [AUC-ROC] = 0.925; sensitivity = 93.75%; specificity = 82.81%)." (PMID 35651679, 2022).
Nephroblastoma (4 papers, 2020 to 2024). An embryonal neoplasm characterized by the presence of epithelial, mesenchymal, and blastema components. "In addition, miR-200c-3p inhibited proliferation, migration, and invasion of nephroblastoma cells via targeting FRS2." (PMID 34524611, 2021). "In addition, the expression of miR-200c-3p is significantly down-regulated in nephroblastoma tissues and cells, and up-regulation of miR-200c-3p inhibits proliferation, migration and invasion of nephroblastoma cells by targeting FRS2." (PMID 34524611, 2021). "High expression of FRS2 has been identified in nephroblastoma and breast cancer." (PMID 32515146, 2020).